BCL2 (BCL2 apoptosis regulator)
Diseases named in the same sentence as BCL2 in open-access papers (continued):
Sharing a sentence is not in itself a finding about the gene and the disease.
prostate carcinoma (continued). "In a recent report, we have shown that another chemopreventive agent curcumin inhibited the expression of antiapoptotic Bcl-2 and Bcl-XL, and induced the expression of proapoptotic Bax, Bak, PUMA, Noxa, and Bim in prostate cancer cells." (PMID 17718901, 2007). "Additionally, a recent in vitro study has shown evidence that doxycycline, in combination with doxorubicin, induces apoptosis of prostate cancer cells by increasing BAX expression and decreasing Bcl-2." (PMID 39796759, 2025). "Additionally, KEGG pathway analysis revealed that AKT1, BCL2, CASP3, and TNF were significantly enriched genes involved in the function of several pathways, including pathways in cancer, Prostate cancer, Chemical carcinogenesis-receptor activation, and others." (PMID 41291087, 2025). "MYC inhibition reduced the expression of BCL-2 mRNA in PC-3 and DU145 prostate cancer cells." (PMID 38756697, 2024). "Interestingly, EADR induced apoptosis in prostate cancer cells by upregulating BAX and downregulating Bcl-2, leading to the subsequent reduction of MMP and activation of caspase-3." (PMID 38966207, 2024). "Crucially, regardless of the Bcl-2 or androgen sensitivity of different prostate cancer cell lines, adenovirus-mediated overexpression of Bax has been shown to trigger apoptosis." (PMID 39554609, 2024). "Herein, WAM inhibited the viability of human prostate cancer LNCaP cells and increased the sub-G1 portion, the cleavage of PARP and caspase 3, and the number of TUNEL-positive cells, and inhibited Bcl-2 in LNCaP cells, implying that the cytotoxicity of WAM is mediated by apoptosis in LNCaP cells." (PMID 38474045, 2024). "Similar results were observed in prostate cancer cells treated with anethole, where the pro-apoptotic effect was evidenced by the activation of caspase-3 and 9, DNA damage, PARP cleavage and induction of Bax/Bcl-2 protein ratio were evident." (PMID 39689117, 2024). "Fucoidan from seaweeds showed anticancer activity by enhancing the chromatin condensation, Bax, cleaved Cas-9 and poly-ADP ribose polymerase, and suppressed Bcl-2, p-PI3K, p-P38, p-Akt, and p-ERK genes in a dose-dependent manner in vitro in DU-145 prostate cancer cells." (PMID 37660108, 2023). "In prostatic cancer, TTN‐AS1 could negatively interact with miR‐193a‐5p, which then adjusted the protein levels of p21, Bax, CyclinD1, and Bcl‐2 to involve in cell apoptosis and proliferation." (PMID 37528740, 2023). "No change in Bcl-2, Bcl-xL, or Bax/Bak expression was observed in prostate cancer PC-3 cells in one study, while other authors have detected Mcl-1 degradation in liver cancer cells." (PMID 36675536, 2023). "Curcusone C is a potential compound with anti-prostate cancer activity, and this effect occurs by targeting the PCBP2 protein, which in turn may affect the TGF/Smad signaling pathway and Bax/Bcl-2 balance." (PMID 37814239, 2023). "Furthermore, our data demonstrate that inhibition of Bcl-2 and Bcl-xL by ABT-263 lowered the cell death threshold in prostate cancer cells, thus rendering both LNCaP and PC3 prostate cancer cells more susceptible to apoptosis induced by ionizing radiation." (PMID 37173959, 2023). "In particular, they show that in LNCap prostate cancer cells, DJ-1, by inhibiting JNK and Bcl2 phosphorylation as well as Beclin1 and Bcl2 dissociation, causes a reduction of microtubule-associated proteins 1A/1B light chain 3B, namely LC3 (MAP1LC3B) and of auto-phagosome formation." (PMID 35563738, 2022).
prostate carcinoma (continued). "In prostate cancer cells, Apl-1 treatment increased PARP cleavage and activated caspase-3 expression, and inhibited the expression of anti-apoptotic proteins p-Akt (ser473), p-mTOR (ser2448), XIAP, and Bcl-2." (PMID 35629355, 2022). "Bcl-2 and Mcl-1 were important targets of STAT signaling in prostate cancer." (PMID 34976194, 2022). "In prostate cancer, it has been described that RUNX2 can bind to the promoter region of antiapoptotic genes and regulate their expression through the recruitment of other cofactors, such as BCL2." (PMID 36510562, 2022). "Moreover, senescent prostate cancer cells, accumulating DNA damage induced by ionizing radiation and PARP inhibition, were killed by the Bcl-2 inhibitors navitoclax and ABT-737." (PMID 34298797, 2021). "The bcl-2 gene was transcriptionally regulated by NF-κB and directly links the tumor necrosis factor α, TNF-α/NF-κB signaling pathway with bcl-2 expression and its prosurvival response in human prostate carcinoma cells." (PMID 33815656, 2021). "In the hormone sensitive LNCaP prostate cancer cell line model, upregulation of BCL-2 is required for progression from an androgen-dependent to androgen-independent state, and overexpression of BCL-2 confers resistance to androgen depletion, protecting cells against apoptosis." (PMID 35008216, 2021). "Additionally, results of the study conducted on twenty-six men with newly diagnosed prostate cancer demonstrated that lycopene might decrease the growth of prostate cancer; however, no significant changes were observed in the expression of markers of apoptosis, Bcl-2, and BAX." (PMID 32859058, 2020). "It has been shown that Bcl-XL, but not Bcl-2 overexpression, another anti-apoptotic biomarker, protects prostate cancer cells against sulforaphane-induced cell death, indicating that Bcl-XL plays a crucial role in sulforaphane’s mechanism for cell damage." (PMID 31671779, 2019). "Single‐agent ABT‐199 demonstrated minimal antiproliferative activity in all the cell lines tested indicating that BCL‐2 is not a critical survival protein in the prostate cancer cells tested." (PMID 31228231, 2019). "In contrast, Bcl-2 overexpression was significantly more in prostate cancers after NHT than in those without NHT." (PMID 30321230, 2018). "Decreased BAX (BCL2 associated X, apoptosis regulator) expression and increased BCL2 (BCL2, apoptosis regulator) expression were observed in all prostate cancer cells (date not shown)." (PMID 30361641, 2018). "In addition, we correlated the results with the expression of the molecular markers (apoptotic and tumor survival) Ki67, Bcl-2, CD10 and syndecan-1 (CD138) for which a prognostic significance in prostate cancer has previously been suggested." (PMID 30321230, 2018). "In addition, IATL treatment significantly suppressed the expression of Bcl-2, suggesting that mitochondrial pathway is involved in IATL-induced apoptosis in prostate cancer cells." (PMID 30541589, 2018). "It is noteworthy that, although Bcl-2 overexpression did not provide protection from DATS-induced apoptosis in one prostate cancer cell line, Bax and Bak knockdown conferred partial resistance." (PMID 28788092, 2017). "No apparent modulation of the anti-apoptotic Bcl-2 or Bcl-xL protein levels was observed in all prostate cancer cell lines treated with platinum drugs and/or TRAIL." (PMID 29182622, 2017).
prostate carcinoma (continued). "Another study indicated that CPT could significantly block activation of JNK and p38 MAPK, which suppressed the expression of Bcl-2 and eventually sensitized DU145 prostate cancer cells to Fas (APO1/CD95)-mediated apoptosis." (PMID 28654902, 2017). "In addition, knockdown of AQP9 resulted in a significant decrease in the expression of the Bcl-2 and with a notable increase in the expression of Bax and cleaved caspase 3, indicated that AQP9 knockdown promoted apoptosis in prostate cancer cells." (PMID 27187384, 2016). "Also the downregulation of SNAI2, ITGA3, BCL2, PGR, IGFPB3 and HOXD10 was previously reported for prostate cancer." (PMID 28005952, 2016). "BCL2 is commonly overexpressed in prostate cancer compared to normal prostate and elevation of BCL2 expression is associated with poor prognosis and suspected in the development of castration-resistant prostate cancer." (PMID 27203547, 2016). "Up-regulation of BCL2 correlates with progressed levels of prostate cancer but the exact role of BCL2 in prostate cancer is not explicit." (PMID 28005952, 2016). "On the other hand, it was reported that exposure to zinc sulfate in human prostate cancer cells increased intracellular levels of zinc, resulting in increased apoptosis, which could be due to increased levels of BAX or decreased Bcl-2 and survivin expression." (PMID 26338969, 2015). "ABT-263 Treatment also reduced the survival of TR9 Ron cells in absence of HGFL, suggesting that Bcl2 is an important survival factor in prostate cancer cells that prevents anoikis even in the absence of Ron activation." (PMID 24980820, 2014). "In prostate cancer, TGF-β-mediated apoptosis involves: (i) caspase 1 activation 80; (ii) up-regulation of pro-apoptotic factors (e.g. Bax, p27KIP1); and/or (iii) down-regulation of antiapoptotic factors (e.g. Bcl-2 and Bcl-xl) 51,81." (PMID 24629090, 2014). "In conclusion, our observations indicated targeting AR, PI3K/Akt, Bcl-2, Src, and EGFR signaling pathway may be a choice for treatment of castration-resistant AR-positive prostate cancers." (PMID 24349321, 2013). "Furthermore, when pargyline was used to treat prostate cancer cells, the expression of pro-apoptotic member NOXA increased significantly, but the expression of anti-apoptotic protein BCL-2 decreased compared with tranylcypromine treatment." (PMID 23900512, 2013). "Prostate cancer cells commonly express three anti-apoptotic Bcl proteins: BCL-XL, BCL-2, and MCL-1." (PMID 24040284, 2013). "The implication of Bcl2 methylation in prostatic cancer is not understood and has to be balanced by the additional decrease expression of pro-apoptotic protein such as Bak and Bik in these cancers." (PMID 24709797, 2013). "For example, celecoxib induced apoptosis by an inhibition of Akt phosphorylation in prostate cancer cells COX-2-positive LNCaP without affecting Bcl-2 level." (PMID 20339581, 2010). "In a study including 20 men who were radio-naïve and underwent prostatectomy for prostate cancer, no patient in this group was Bcl-2 positive." (PMID 19589167, 2009). "More recently, celecoxib, a potent and selective Cox-2 inhibitor, was shown to induce apoptosis in human prostate cancer cells by blocking Akt activation, independent of Bcl-2 signaling." (PMID 17201910, 2007). "Notably, a flavonoid extracted from D. kaki L. leaves exhibited a similar pattern by reducing MMP, suppressing Bcl-2 expression, and enhancing Bax and cleaved caspase-3 levels in PC3 prostate cancer cells, suggesting the induction of apoptosis via the mitochondrial-mediated pathway." (PMID 38966207, 2024). "ADA has been shown to induce cell death in hepatoma cells by regulating the ratio of BAX and BCL-2, to impede proliferation in ovarian cancer via GOT1 inhibition, and to exert pronounced anti-cancer activity in prostate cancer cells by inducing DNA damage, cell cycle arrest and apoptosis." (PMID 39175546, 2024).
prostate carcinoma (continued). "We here found that LPHNs induced the growth of prostate cancer cells and that the activation of LPHNs was associated with phosphorylation of JAK2/STAT3, but not Akt or ERK1/2, as well as the increased expression of Bcl-2." (PMID 39000396, 2024). "To further elucidate the mechanism of ZQD in inhibiting prostate cancer and unveil the role of miR-143 in mediating the effects of ZQD, we performed bioinformatics analysis using Targetscan, which suggested a direct binding site between miR-143 and the 3’-UTR of Bcl-2." (PMID 34170852, 2021). "Although accumulated evidence suggests the existence of a molecular link between VD3 and Bcl-2 in multiple tumor types, proapoptotic effects of VD3 remain to be elucidated at the cell biological level and in animal studies for each tumor type, including prostate cancer." (PMID 32831047, 2020). "Therefore, as a single agent inhibiting TGF-β signaling and Bcl-2 expression, naftopidil could be an effective inhibitor of the TGF-β/acetylated KLF5 signaling axis for overcoming DTX resistance in prostate cancer." (PMID 32685011, 2020). "Accordingly, these results suggest that the TGF-β/acetylated KLF5/BCL2 signaling axis mediates DTX resistance in prostate cancer and that targeting this signaling axis might be a novel therapeutic approach for the treatment of chemo-resistant prostate cancer." (PMID 32685011, 2020). "Gingerol might induce apoptosis both in vitro, using PC-3 prostate cancer cells, and in vivo, using mice with prostate cancer xenografts, by increasing the level of cleaved Poly (ADP-ribose) polymerase (PARP) and reducing the levels of anti-apoptotic protein Bcl-2." (PMID 30823649, 2019). "However, Bcl-2 expression was not significantly correlated with the Gleason Score or Pathological N of prostate cancer, and overall survival of prostate cancer patients." (PMID 31534497, 2019). "In addition, we could not detect any significant changes in the amount of antiapoptotic Bcl-2 family proteins Bcl-2 and Bcl-xL in the cisplatin/LA-12 and TRAIL combination-treated prostate cancer cells." (PMID 29182622, 2017). "The absence of BCL-2 protein expression is reported in prostate cancer." (PMID 26683658, 2015). "Our data also demonstrated that the inhibition of AKT activity can enhance the upregulation of Bax expression and downregulation of Bcl-2 expression induced by baicalein, suggesting that AKT may be at the upstream of the baicalein-induced apoptosis of prostate cancer cells." (PMID 25957503, 2015). "Furthermore, BCL-2 expression is negative in androgen-dependent, but increased in hormone insensitive prostate cancers and correlated with poor prognosis." (PMID 26683658, 2015). "The prostate cancer antigen gene 3 (PCA3) is embedded in an intron of a second gene BMCC1 (Bcl2-/adenovirus E1B nineteen kDa-interacting protein 2 (BNIP-2) and Cdc42GAP homology BCH motif-containing molecule at the carboxyl terminal region 1) which is also upregulated in prostate cancer." (PMID 24040105, 2013).
prostate carcinoma (continued). "Induction of Bax and Bak (proapoptotic), down-regulation of Bcl-X(L) and Bcl-2 (anti-apoptotic), induction of WAF1/p21 and KIP1/p27, a decrease in cyclins D1, D2, and E, and a decrease in cdk2, cdk4, and cdk6 expression have been shown to occur in prostate cancer PC3 cells, following Pg treatment." (PMID 24250463, 2012). "Meanwhile, there are several genes which mediate the miR-34a induced tumor growth inhibition, such as BCL2, E2F3 and MYCN in neuroblastoma, mitogen-activated protein kinase kinase 1 (MEK1) in human chronic myelocytic leukemia cell line K562 and SIRT1 in prostate cancer PC3 cells." (PMID 22457788, 2012). "Galectin-3 and MCP have different effects on apoptosis: galectin-3 has a BH1 domain of BCL2 that can protect cells from apoptosis and transfection with the lectin makes T-cells resistant to this type of cell death; MCP, in contrast, promotes apoptosis in angiosarcoma and prostate cancer cell lines." (PMID 21494626, 2011). "Moreover, in prostate cancer, miR-34a is markedly underexpressed in cancer stem cell (CD44+) subpopulations; enforced re-expression of miR-34a significantly inhibits tumor regeneration and metastasis, likely through targeting of stemness and survival regulators such as CD44, NOTCH, MYC, and BCL-2." (PMID 41465187, 2025). "Previous studies showed the capability of 3-hydroxytyrosol and chlorogenic acid to reduce BCL-2 and caspase-3 gene and protein expression, respectively, while gentisic acid could interact with fibroblast growth factor 1 (FGF1), whose levels are increased in prostate cancer." (PMID 36234818, 2022). "This suggested that hyper-activation of STAT5 signaling per se may not act as an oncogene in the prostate, but it could tweak prostate cancer progression in a more proto-oncogenic role driving e.g., enhanced Myc, Bcl2 or D type cyclin family member expressions." (PMID 31269779, 2019). "Similarly, BCL2 repositions in a BCL2-positive cervical squamous carcinoma, but not in a BCL2-negative cervical squamous carcinoma, nor in breast or prostate cancer." (PMID 27507988, 2016). "RT-PCR studies indicated that Myc, as well as BCL2, were significantly down regulated in PC3-AZD20 cells following treatment with CTA095, indicating that this down regulation may contribute to the induction of apoptosis in Src inhibitor resistant prostate cancer cells." (PMID 23967135, 2013). "However, stress-induced increase in several antiapoptotic genes, such as bcl-2, clusterin, insulin-like growth factor binding protein-2 (IGFBP-2), IGFBP-5 and heat-shock protein 27, have been shown to have important functions in the AI progression of prostate cancer after castration." (PMID 19844233, 2009). "Although levels of BCL2 mRNA (a pro-survival gene) were not significantly affected by Par-4 overexpression in HT29 colon cancer cells, we included BCL2 in immunoblotting assays since Par-4 has been shown to regulate BCL2 mRNA in prostate cancer cell lines." (PMID 20433755, 2010). "For instance, RU486 may induce apoptosis in LNCaP prostate cancer line with a mechanism not antagonized by progesterone or hydrocortisone; conversely, an additive effect of the combination of RU486 with the two steroids on the increase in DNA fragmentation and Bcl2 downregulation was observed." (PMID 33053110, 2020).